CAPN10 (calpain 10)
Description:
Calcium-regulated non-lysosomal thiol-protease which catalyzes limited proteolysis of substrates involved in cytoskeletal remodeling and signal transduction. May play a role in insulin-stimulated glucose uptake.
Synonyms: CANP10; NIDDM1
Tractability: Antibody: its Gene Ontology location is reachable by antibodies, with medium confidence. PROTAC: ubiquitination databases record sites on it; its protein half-life has been measured.
Safety:
Unwanted effects reported when the protein is acted on. In parentheses: how it was acted on, where the effect was seen, and who reports it.
new-onset posttransplant diabetes mellitus (source: ClinPGx)
new-onset posttransplant diabetes mellitus (PTDM) (source: ClinPGx)
Gene: Protein-coding gene on chromosome 2 (240,586,383 to 240,617,705, forward strand). Ensembl gene ENSG00000142330.
Subcellular location (Human Protein Atlas): Cytosol; Mitochondria
Pathways (Reactome):
Extracellular matrix organization: Degradation of the extracellular matrix
Gene Ontology:
Molecular function: calcium-dependent cysteine-type endopeptidase activity; protein binding; cytoskeletal protein binding; SNARE binding
Biological process: cellular response to insulin stimulus; positive regulation of D-glucose import; positive regulation of insulin secretion; proteolysis; type B pancreatic cell apoptotic process; cellular component disassembly involved in execution phase of apoptosis; regulation of actin cytoskeleton organization; vesicle-mediated transport to the plasma membrane
Cellular component: cytosol; mitochondrion; cytoplasm; plasma membrane
Genetic constraint (gnomAD): Loss-of-function variants: 71 observed, 77.13 expected, observed/expected ratio (o/e) 0.92, 90% interval 0.76 to 1.12. The upper end of that interval is the gene's LOEUF score, 1.12, which puts it in group 4 of 6, group 1 being the genes least tolerant of losing a copy. Missense variants: 849 observed, 911.93 expected, observed/expected ratio (o/e) 0.93, 90% interval 0.88 to 0.99. Synonymous variants: 437 observed, 399.89 expected, observed/expected ratio (o/e) 1.09, 90% interval 1.01 to 1.18.
Homologues: Orthologues: chimpanzee CAPN10 (99% identical), macaque CAPN10 (95% identical), mouse Capn10 (81% identical), rat Capn10 (81% identical), pig CAPN10 (80% identical), guinea pig CAPN10 (79% identical), rabbit CAPN10 (73% identical), dog CAPN10 (60% identical), zebrafish capn10 (49% identical), tropical clawed frog capn10 (48% identical), Caenorhabditis elegans tra-3 (23% identical), Caenorhabditis elegans clp-6 (22% identical), and 6 more. Paralogues in human: CAPN5 (28% identical), CAPN12 (26% identical), CAPN11 (26% identical), CAPN8 (26% identical), CAPN1 (26% identical), CAPN2 (26% identical), CAPN3 (25% identical), CAPN6 (25% identical), CAPN14 (24% identical), CAPN9 (24% identical), CAPN13 (22% identical), ADGB (17% identical), and 8 more.
Diseases named in the same sentence as CAPN10 in open-access papers:
CAPN10 is named in the same sentence as 52 diseases in open-access papers, as found by Europe PMC text mining. Sharing a sentence is not in itself a finding about the gene and the disease. The quoted sentences say what the papers report.
type 2 diabetes (41 papers, 2005 to 2025). "Variants in the CAPN10 gene (rs3792267, rs2975760, and rs5030952) have been associated with impaired insulin secretion and increased type 2 diabetes mellitus risk across multiple ethnic groups, including Asians." (PMID 40944253, 2025). "Calpain10 (CAPN10) gene was the first identified susceptibility gene for type 2 diabetes mellitus and closely related to insulin sensitivity." (PMID 37727373, 2023). "CAPN10, which encodes calpain 10 and is involved in insulin function and secretion, has been identified as a risk gene for type 2 diabetes, and specific CAPN10 variants have been associated with PCOS." (PMID 37371662, 2023). "Calpain 10 (CALP10) is a biomarker of type 2 diabetes mellitus, with some of its single-nucleotide polymorphisms (SNPs) influencing PCOS development." (PMID 38213994, 2023). "In the initial years of the 21st century, polymorphism of the CAPN10 (calpain-10 gene) was reported to increase the risks of type 2 diabetes and decrease glucose disposal." (PMID 38069105, 2023). "It was documented that calpain-10 is associated with several diseases, most notably type 2 diabetes mellitus." (PMID 38069105, 2023). "Some scientists identified that the calpain-10 (CAPN10) gene is the first candidate type 2 diabetes mellitus (T2DM) gene, which is associated with decreased glucose tolerance and insulin resistance (IR) phenotypes by genome-wide linkage and positional cloning." (PMID 31552190, 2019). "One of the candidate genes displaying a 12-h rhythmic FIRMAGene score in BAT was the type 2 diabetes-associated gene Capn10 which encodes for eight known protein isoforms in humans and has been reported as a target of the splicing factor ZRANB2." (PMID 31443305, 2019). "Calpain-10 (CAPN10) is the calpain family protease identified as the first candidate susceptibility gene for type 2 diabetes mellitus (T2DM)." (PMID 30425305, 2018). "Calpain-10, a member of atypical calpains, is shown to be associated with type 2 diabetes and insulin resistance due to a variation in the calpain-10 gene in type 2 diabetes population with a single nucleotide polymorphisms at a rare allele SNP 4420,21." (PMID 29089532, 2017). "Previous study have reported that genetic variation in the Calpain-10 gene was associated with an increased risk for type 2 diabetes mellitus in certain human population groups has been reported by Horikawa groups." (PMID 25226618, 2014). "The potential influence of comparatively rare CAPN10 haplotypes on type 2 diabetes risk in this population requires further evaluation." (PMID 24059590, 2013). "TCF7L2 rs7903146, KCNJ11 rs5219, PPARγ rs1801282 and CAPN10 rs3842570, rs3792267, and rs5030952 were typed and associations with type 2 diabetes and phenotypic traits examined." (PMID 24059590, 2013). "Clearly, further investigations are warranted to understand the role of CAPN10 variants and their interplay for the risk of type 2 diabetes in SSA." (PMID 24059590, 2013). "Variation in the calpain-10 gene was reported to be linked and associated with type 2 diabetes mellitus (T2DM) susceptibility in a Mexican American population." (PMID 22384174, 2012). "In humans, mutations of CAPN3 were shown to be responsible for muscular dystrophy by forward genetics, and an intron polymorphism of CAPN10 was reported to be associated with type 2 diabetes by statistical genetics." (PMID 20686710, 2010). "Calpain-10 is a cysteine protease that plays a role in insulinsecretion and action, and genetic studies have shown that variation in the gene (CAPN10) encoding calpain-10is associated with type-2 diabetes." (PMID 17389770, 2007). "Among them, genes of the glucose metabolism, such as CAPN10, encoding for calpain, a calcium-sensitive cysteine protease associated with type 2 diabetes, and its inhibitor CAST, involved in obesity-induced AT inflammation, were up-regulated in this subject group." (PMID 30838002, 2019).
type 2 diabetes (continued). "For instance, in the collaborative meta-analysis for the association of CAPN10 haplotypes with Type 2 Diabetes mellitus, the authors report a marginally significant OR of 1.09 (1.00, 1.18) for the "1-2-1" haplotype and similar results for two haplogenotypes that include this haplotype." (PMID 21247440, 2011). "Calpain-10, a constituent of the atypical calpains, stands as the inaugural susceptibility gene identified for type 2 diabetes (T2DM)." (PMID 38069105, 2023). "The same also has a more critical link to family history and lineage compared to Type I. Any mutations in proteins such as TCF7L2, ABCC8, GLUT2, and CAPN10 favor the progression of Type 2 diabetes because they could influence the production or mechanism of action of insulin." (PMID 34943006, 2021). "CAPN10 polymorphisms in SSA might influence type 2 diabetes risk only in certain combinations." (PMID 24059590, 2013). "Calpain-10 was the first gene to be identified influencing the risk of type 2 diabetes (T2D) by positioning cloning." (PMID 19688040, 2009). "The calpain 10 gene (CAPN10) has been associated with type 2 diabetes (T2DM), a complex metabolic disorder with increased risk of cardiovascular disease." (PMID 18698425, 2008). "Genes associated with complex diseases, such as asthma‐interleukin‐13 and type 2 diabetes (CAPN10), have also been reported to exhibit signatures of positive selection in various studies." (PMID 39364034, 2024). "For instance, Calpain-10 (CAPN10), implicated in insulin resistance, has been investigated due to PCOS women's predisposition to glucose intolerance and type 2 diabetes mellitus (T2DM)." (PMID 37881324, 2023). "Its involvement in type 2 diabetes mellitus is linked to genetic variations in the CAPN10 gene, which encodes calpain-10." (PMID 38069105, 2023). "Considering that most PCOS women are at an increased risk of developing glucose intolerance and type 2 diabetes mellitus (T2DM), the gene Calpain 10 (CAPN10), located on the 2q chromosome and usually associated with insulin resistance, has been investigated." (PMID 35740328, 2022). "Susceptibility genes for type 2 diabetes have been related to CFRD, specifically CAPN10 (calpain 10; OMIM * 605286) and TCF7L2 (transcription factor 7-like 2; OMIM * 602228)." (PMID 35887806, 2022). "Previous studies investigated in various populations the associations between the polymorphisms of the ADCY5 gene (rs11708067, rs2877716), CAPN10 gene (rs2975760, rs3792267), JAZF1 gene rs864745, and type 2 diabetes." (PMID 34440550, 2021). "Prior to the IBD GWAS, the neighboring genes CAPN10 and GPR35 had both previously been linked with disease in a GWAS for type 2 diabetes mellitus." (PMID 25805994, 2015). "Two CAPN10 haplotypes tended to protect against type 2 diabetes: 211 (aOR, 0.32; 95% CI, 0.03-1.92; p = 0.31) and 221 (aOR, 0.73; 95% CI, 0.48-1.10; p = 0.13)." (PMID 24059590, 2013). "Genetic variations in the calpain-10 gene (CAPN10), in particular the at-risk diplotype (112/121), were previously implicated with increased risk of type 2 diabetes (T2D)." (PMID 20470430, 2010). "Analysis of the type-2 diabetes-associated SNPs CAPN10 g.4834T>C and TCF7L2 g.98386G>T, found their MAFs (23.1% and 24.8%, respectively) to be almost twice as common as type-2 diabetes in the Indian population (11.6%)." (PMID 18248681, 2008). "Of note was the Kashmiri group, which had significantly higher MAFs than the other groups for the CAPN10 g.4834T>C and TCF7L2 g.98386G>T SNPs associated with type-2 diabetes risk." (PMID 18248681, 2008). "Previous studies have shown that polymorphisms of ADCY5, CAPN10, and JAZF1 genes may be associated with an increased risk of type 2 diabetes." (PMID 34440550, 2021). "Indeed, some CAPN10 haplotypes nominally confer a protection against type 2 diabetes in our study population (ORs, 0.45-0.72)." (PMID 24059590, 2013).
type 2 diabetes (continued). "For example, loss of function of the full-length isoform of calpain 3 results in limb girdle muscular dystrophy type 2A, knocking out alleles of mouse CAPN 8 and CAPN 9 results in ethanol-induced gastric injury, and aberrant calpain 10 activation results in type 2 diabetes." (PMID 23855590, 2013). "Some polymorphisms in CAPN10 and CAPN5 have been shown to be risk factors for type II diabetes." (PMID 23055945, 2012). "The key results from this study were that 1) calpain-10 mRNA levels were elevated in pancreatic islets of patients with type 2 diabetes and 2) there was a positive correlation between calpain-10 expression and insulin release in response to arginine in non-diabetic but not in diabetic donors." (PMID 19688040, 2009). "CAPN10 gene has been associated with type 2 diabetes in some studies, but other analyses failed to reproduce this finding." (PMID 18698425, 2008). "For instance, the role of MTNR1A and MTNR1B, THADA, CAPN10, and PPAR-γ2 in pathology of type 2 diabetes and obesity has been confirmed." (PMID 34949963, 2021). "In linear regression models, we investigated whether TCF7L2 and CAPN10 variants were associated with phenotypic characteristics among controls without type 2 diabetes, including loge-normalized FPG, waist circumference, BMI, systolic and diastolic blood pressure and urinary albumin." (PMID 24059590, 2013). "Apart from being a strong candidate for T2DM, the CAPN10 gene has been widely evaluated in traits such as PCOS and idiopathic hirsutism due to the fact that PCOS and type-2 diabetes share a number of etiologic factors." (PMID 22384174, 2012). "The study therefore concluded that the genetic variation in CAPN10, and not GPR35, was responsible for the disease susceptibility, and no further evidence for a role of GPR35 in type 2 diabetes has since been reported." (PMID 25805994, 2015).
diabetes (33 papers, 2007 to 2025). "Some genes selected for this study, such as TCF7L2, FTO (rs9939609 variant), and CAPN10, have been shown to be associated with diabetes-related traits such as HbA1c levels, when diets are low in MUFAs and high in SFAs." (PMID 39275336, 2024). "The Calpain-10 gene was the first diabetes gene identified by cloning and encoding the Calpain-10 protein." (PMID 38139275, 2023). "In terms of diabetes, polymorphisms of the calpain-10 gene can modify insulin secretion and glucose disposal." (PMID 38069105, 2023). "The polymorphism of calpain-10 has been linked and associated with diabetes susceptibility, glucose homeostasis, insulin secretion and insulin activation." (PMID 26120352, 2015). "Genetic variations in CAPN10, encoding the calpain-10 protease, also modulate diabetes risk, and data imply that calpain-10 may also act on intact TUG or on the TUG C-terminal product." (PMID 36246906, 2022). "Of the diabetes-related genes, fine mapping and positional cloning suggested that the calpain-10 (CAPN10) gene might serve as an important T2D susceptibility gene." (PMID 20470430, 2010). "We use FHS 100K SNPs in an in silico replication analysis that tests the hypothesis that SNPs in LD with published causal variants in PPARG, ABCC8, TCF7L2, CAPN10, and HNFa are associated with diabetes and related quantitative traits." (PMID 17903298, 2007). "Taken together, calpains, especially calpain-10 and −3, and μ-calpain play an important role in the pathogenesis of diabetes, such as insulin resistance, insulin secretion, glycogen synthesis, glucose transporter turnover and ED." (PMID 26120352, 2015). "An influence of SNPs within the calpain-10 gene (CAPN10) on the occurrence of diabetes in Polish Caucasian kidney transplant recipients has also been described." (PMID 22569928, 2012). "Although Calpain 10 is the first identified diabetes gene through a genome scan., little is known about its protease activity and physiological functions." (PMID 22536436, 2012). "These SNPs represent several distinct physiological pathways, including blood coagulation (F3), endothelial and hematopoietic stem cell proliferation (KITLG), protease pathways contributing to diabetes (CAPN10), and extracellular matrix remodeling (MMP2)." (PMID 19351393, 2009). "The interaction between Calpain-10 and sodium channels may be especially interesting in the context of diabetes and the development of neuropathic pain, a common complication of diabetes." (PMID 38514708, 2024). "Since CAPN10 is expressed in various tissues, target substrates of the protein and other related factors could act together in development of diabetes." (PMID 30425305, 2018). "Calpain-10 is the first calpain gene identified in diabetes." (PMID 26120352, 2015). "An association of T2DM with the calpain 10 (CAPN10) gene was initially identified, and later, its association with the transcription factor 7-like 2 (TCF7L2) gene, whose genetic variants in affected individuals increase the risk of diabetes by ∼1.5 times." (PMID 24894908, 2014). "Significant random or apparently variation occurs in several other diabetic traits (i. e. glycaemia, CAPN10, suggesting that periodic or episodic physiological variation might be a common feature of diabetes in general as a normal feature of hunger and gut emptying." (PMID 31661517, 2019).